STAT3 (signal transducer and activator of transcription 3)
Diseases named in the same sentence as STAT3 in open-access papers (continued):
Sharing a sentence is not in itself a finding about the gene and the disease.
gastric cancer (continued). "Genetic ablation of STAT3 activity triggered ferroptosis through lipid peroxidation and Fe2+ accumulation in gastric cancer cells." (PMID 38341410, 2024). "Preclinical studies have demonstrated the efficacy of STAT3 inhibitors in controlling gastric cancer, highlighting the potential of targeting this pathway for therapeutic intervention." (PMID 39309860, 2024). "Immunohistochemistry further clarified the expression of MAP3K6, MMP24, and STAT3 in gastric cancer cells after salidroside treatment." (PMID 38436092, 2024). "The overexpression of STAT3 helps HER2-positive gastric cancer cells develop resistance to trastuzumab, often with KRAS gene mutations." (PMID 39309860, 2024). "This indicates that STAT3 indirectly affects IL-10’s influence on the proliferation, invasion, and migration of gastric cancer cells." (PMID 39840050, 2024). "In the present study, we used a specific activation model of the gp130/Stat3 pathway, the homozygous Gp130FF mutant mouse of gastric cancer, that is, driven primarily by inflammation." (PMID 37957015, 2024). "The interaction between STAT3 and MSK1 at the NFATc2 promoter drives H3S10 phosphorylation-dependent transcription, which in turn activates inflammatory pathways associated with gastric cancer genesis." (PMID 39309860, 2024). "Regulatory T (Treg) cells expressing the Foxp3 transcription factor play a critical role in promoting the stemness of gastric cancer cells through the IL13/STAT3 pathway and also help in reducing overactive immune responses within the tumor microenvironment." (PMID 39605357, 2024). "Qingqing Zhou and colleagues highlighted the role of VPS35 in increasing the growth and metastatic spread of gastric cancer cells through the IL-6/STAT3 signaling pathway." (PMID 39309860, 2024). "In gastric cancers, the loss of PTPRD induced CXCL8 and promoted angiogenic and metastatic events via the STAT3 and ERK signalling pathways." (PMID 38339334, 2024). "PN has been shown to suppress the STAT3 signaling pathway in SGC-7901/DPP gastric cancer cells, resulting in apoptosis and enhanced drug chemosensitivity." (PMID 38397437, 2024). "In summary, gypenoside reduced the phosphorylation of STAT3 and inhibit the expression of PD-L1 in gastric cancer cells." (PMID 38482051, 2024). "Jianzheng Wang and colleagues also reported that bone marrow fibroblasts (BMFs) can increase the expression levels of IL-6, TGF-β1, STAT3, and p-STAT3, thus promoting gastric cancer metastasis in a mouse model." (PMID 39309860, 2024). "STAM2 knockdown has been reported to inhibit proliferation, migration, and invasion by affecting the JAK2/STAT3 signaling pathway in gastric cancer." (PMID 39060946, 2024). "In tumor, silent STAT3 can inhibit the activity of BGC‐823 human gastric cancer cell line and induces apoptosis." (PMID 39346794, 2024). "-Inhibits IL-6 expression, induces JAK and STAT3 phosphorylation, and down-regulates STAT3-mediated protein Bad, Bcl-2, and Bax expression to treat gastric cancer." (PMID 38397559, 2024). "This work provides a comprehensive overview of the current understanding of STAT3 in gastric cancer and offers a foundation for future research aimed at improving therapeutic outcomes in this challenging disease." (PMID 39309860, 2024). "Meanwhile, hsa-miR-26b-5p directly interacts with PDE4B and CDK8, thereby downregulating STAT3 phosphorylation and nuclear translocation, and promoting gastric cancer cell proliferation." (PMID 38796629, 2024).
gastric cancer (continued). "Ting Li and colleagues investigated cellular feedback mechanisms and reported an IL6-induced positive regulatory circuit in which miR-520d-5p modulates cyclophilin B (CypB) mRNA, influencing the growth of gastric cancer via changes in STAT3 phosphorylation." (PMID 39309860, 2024). "In vitro assays elucidated XYA-2’s capacity to impede STAT3 phosphorylation in gastric cancer cells, resulting in diminished cellular activity and suppressed cell proliferation." (PMID 38250721, 2024). "In gastric cancer, up-regulation of IL-17 activates STAT3 signaling to promote tumor burden and metastasis." (PMID 39906741, 2024). "Human triple-negative breast and gastric cancer xenografts have been demonstrated to regress in response to WZ-2–033, a new STAT3 inhibitor." (PMID 38273392, 2024). "In gastric cancer, miR-3-515p carried by CircCUL3 can activate signal transducer and activator of transcription 3 (STAT3)." (PMID 39609317, 2024). "Yangbing Jin and colleagues reported that the interaction of EGR1/TGF-β1/CD44s/STAT3 signaling between mesenchymal cells and gastric cancer cells induces EMT and the stem phenotype, leading to the peritoneal metastasis of gastric cancer cells." (PMID 39309860, 2024). "In this study, we explored the critical role of the STAT3 signaling cascade in the pathogenesis of gastric cancer, its contribution to drug resistance, and its involvement in the metastatic process." (PMID 39309860, 2024). "This reduction in interaction decreases the transcriptional activation of IL-6, consequently attenuating the IL-6/STAT3 signaling-mediated expression of PD-L1 and M2 macrophage polarization, thus slowing the progression of gastric cancer." (PMID 39309860, 2024). "Using mouse models, they showed that high miR-375 levels can decrease the activity of the JAK2/STAT3 pathway, leading to the downregulation of PD-L1 in gastric cancer." (PMID 39309860, 2024). "EGCG also exerts inhibitory effects on VEGF level and secretion triggered by IL-6, as well as gastric carcinoma cells’ angiogenesis by suppressing STAT3 activity." (PMID 38611849, 2024). "In vitro cytotoxicity, immunoblot analysis, and OCR testing clearly revealed that this compound not only had strong inhibitory activities on the STAT3 protein, but also exhibited high selectivity for gastric cancer cells." (PMID 38023173, 2023). "Still, considering our findings in bladder cancer and theirs in gastric cancer, it is plausible to postulate that blockade of the STAT3 signaling pathway seems to be a general mechanism of sertindole’s anticancer action." (PMID 37511611, 2023). "STAT3 is constitutively activated in different types of cancer, e.g., breast, lung, prostate, and gastric cancer." (PMID 38067351, 2023). "Targeting STAT3 with small molecules is a promising strategy for halting the progression of gastric cancer." (PMID 38023173, 2023). "IL-17a secretion by CAFs markedly enhances tumorigenic effects of gastric cancer through the JAK2/STAT3 pathway in the gastric cancer cells in vitro, with CAFs acting as an independent risk factor for DFS and DSS." (PMID 37046676, 2023). "As p-STAT3 is a molecular marker of proliferation, our findings suggest that PA blocks the proliferation of human gastric cancer cells by inhibiting p-STAT3 and p-JAK2 expression." (PMID 36672337, 2023). "A correlation between STAT3 activation and the invasion, migration, and prognosis in gastric cancer was reported, as a positive correlation between STAT and VEGF expression was observed in this type of cancer." (PMID 37936608, 2023). "We also determined the biological effects of these STAT3 inhibitors on ATP production and oxygen consumption rate in gastric cancer cells." (PMID 38023173, 2023).
gastric cancer (continued). "In gastric cancer cells, STAT3 is typically activated and localized in the nucleus, exhibiting high expression levels." (PMID 37637038, 2023). "For instance, asiatic acid derivatives have been found to suppress JAK2 and STAT3 activation, inhibiting gastric cancer cell proliferation and invasion." (PMID 37375849, 2023). "Our findings demonstrated that PA exerted anti-gastric cancer effects by regulating key molecules in the signal transduction and activation of a transcription 3 (STAT3) protein inhibitor of the activated STAT 3 (PIAS3) signaling pathway." (PMID 36672337, 2023). "Since STAT3 can regulate the expression of multiple genes that promote proliferation, anti-apoptosis, angiogenesis, and immune escape in gastric cancer cells, presence of lncRNA RPSAP52 enhances the malignant features of gastric cancer." (PMID 37894282, 2023). "This study examines if sugiol can induce apoptosis in human gastric cancer cells and inhibit their proliferation by modulating STAT3." (PMID 38004394, 2023). "In this paper, we investigated the promotion effects of TNF+ Tregs on stemness in gastric cancer cells through the IL13/STAT3 signaling pathway." (PMID 37534250, 2023). "A long non-coding RNA (HOTAIR) targets miR-454-3p to upregulate the STAT3/Cyclin D1 in gastric cancer cells to promote the proliferation and progression of cancer." (PMID 36769170, 2023). "Our observation that PA inhibits human gastric cancer cell proliferation and metastasis has prompted us to further analyze its effects on STAT3 phosphorylation." (PMID 36672337, 2023). "Taken together, our results indicate that GDF15 expression is associated with aggressive gastric cancer by promoting STAT3 phosphorylation, suggesting that the GDF15-STAT3 signaling axis is a potential therapeutic target against gastric cancer progression." (PMID 36769245, 2023). "SNHG16 sponged miR-135a and promoted Janus-activated kinase 2 (JAK2) and transcription Factor 3 (STAT3) expression in gastric cancer." (PMID 36949429, 2023). "The activation of STAT3 was positive in early gastric cancer, poorly differentiated adenocarcinoma and metastatic lymph node tissues." (PMID 37062850, 2023). "CCAT5 binds to the C-end domain of STAT3 and inhibits STAT3Y705 dephosphorylation mediated by SHP-1, thereby inducing STAT3 nuclear entry and metastatic activation, which promotes gastric cancer progression." (PMID 38203502, 2023). "Hematoxylin and eosin (H&E) staining helped distinguish the gastric cancer tissues from the paracancerous tissues, and an immunohistochemical analysis revealed that p-STAT3 levels were 60% higher in the gastric cancer samples than in the paracancerous tissues." (PMID 36672337, 2023). "There is a direct positive correlation between RACGAP1 and AURKA in gastric cancer, and STAT3 and AURKA are all closely related to the neuroendocrine transformation of PCa." (PMID 37196108, 2023). "Further research is warranted to explore the full potential of sugiol as a therapeutic agent and its potential application in treating gastric cancer and other malignancies characterized by dysregulated STAT3 activity." (PMID 38004394, 2023). "We also investigated the molecular mechanism by which LOC339059, as a tumor suppressor, inhibits PDL1 and macrophage M2 polarization by modulating the activity of the IL-6/STAT3 axis in gastric cancer cells." (PMID 38001573, 2023). "We employed a comprehensive gene expression analysis through data mining of publicly available databases to assess the role of the signal transducer and activator of transcription 3 (STAT3) in gastric cancer drug efficiency." (PMID 36979673, 2023). "In a mouse model, the pro-inflammatory cytokine-driven downregulation of EZH2 maintains SASP by demethylating H3K27me3 marks and promotes peritoneal tumor formation in gastric cancer (GC) via JAK/STAT3 signaling." (PMID 37049920, 2023).
gastric cancer (continued). "The JAK/STAT signaling pathway also regulates ferroptosis-related molecules; for example, propofol, a widely used anesthetic, inhibits STAT3 expression by upregulating miR-125b-5p and accelerating ferroptosis in gastric cancer cells." (PMID 38111578, 2023). "The WB results suggested that p-STAT3 levels were lower in the PA-treated human gastric cancer cell lines (MGC-803, AGS, and SGC-7901) than in the BSA-treated cell lines and were significantly correlated with PA concentration." (PMID 36672337, 2023). "The widely used anesthetic propofol inhibited STAT3 expression via increased miR-125b-5p and accelerated gastric cancer cell ferroptosis." (PMID 36944609, 2023). "In gastric cancer, OSM promotes gastric cancer growth and metastasis through STAT3/FAK/Src signaling." (PMID 38034950, 2023). "In gastric cancer, STAT3 intricately governs cell proliferation, differentiation, apoptosis, and angiogenesis, making it an attractive target for drug development." (PMID 38023173, 2023). "IL-6 can regulate M2-type macrophage polarization by activating the JAK2/STAT3 signaling in gastric cancer cells." (PMID 37679346, 2023). "Our results indicated that PIAS3 mRNA levels increased gradually as the PA treatment duration or the PA concentration increased, consistent with our findings relating to p-STAT3 protein expression in human gastric cancer and normal cells." (PMID 36672337, 2023). "Under normal circumstances, p-STAT3 is located in the nucleus in an activated state and is highly expressed in gastric cancer cells." (PMID 36672337, 2023). "The activation of the STAT3/VEGFA signaling axis by lncRNA PVT1 has been found to enhance angiogenesis in gastric cancer." (PMID 37915049, 2023). "In gastric cancer, miR-93-5p played an oncogenic role by activating the STAT3 pathway, and upregulation of miR-93-5p was found to be associated with shorter OS of patients." (PMID 37215455, 2023). "The immunohistochemical staining revealed that p-STAT3 levels were higher in the gastric cancer tissues than in the control tissues." (PMID 36672337, 2023). "We found that TNF+ Tregs released a high level of the anti-inflammatory cytokine IL13, which promotes the malignant biological function of gastric cancer cells by activating STAT3." (PMID 37534250, 2023). "GB1107 has also been shown to inhibit tumor growth in orthotopic gastric cancer-bearing mice by significantly reducing STAT3 and β-catenin activation." (PMID 36914828, 2023). "The expression of STAT3 and phosphorylated STAT3 increased in gastric cancer in comparison with normal stomach." (PMID 37062850, 2023). "In our results, we found that GDF15 inhibition induced cell cycle arrest in gastric cancer cells by inhibiting STAT3 activation." (PMID 36769245, 2023). "Comprehensive STAT3 silencing studies in gastric cancer have revealed that STAT3 is an important factor in cancer progression." (PMID 38067351, 2023). "The WB analyses demonstrated that p-STAT3 levels were higher in the five clinical gastric cancer tissues (T) than in the matched adjacent tissues (N)." (PMID 36672337, 2023). "TQ showed anti-cancer effects by inducing apoptosis and blocking STAT3 phosphorylation in gastric cancer cells; reduced STAT3 showed a reduction in JAK2 and c-Src activity." (PMID 37049544, 2023). "Cucurbitacin B, as a STAT3 inhibitor, can effectively inhibit gastric cancer progression by preventing STAT3 activity." (PMID 38017510, 2023). "It has been reported that berberine suppressed EGFR/STAT3 signaling pathways in gastric cancer cell lines." (PMID 36770659, 2023). "miR-375 overexpression suppresses PD-L1 expression in gastric cancer via the JAK2/STAT3 signaling pathway." (PMID 37813900, 2023). "STAT3 is a cytoplasmic transcription factor highly expressed in gastric cancer tissues, and its aberrant activation can promote tumor formation by regulating tumor cell proliferation, angiogenesis, migration and immune evasion." (PMID 37608281, 2023).
gastric cancer (continued). "It has been noticed that tumor‐linked neutrophils can produce IL‐17A, promoting epithelial‐mesenchymal transition (EMT) in gastric cancer via JAK2/STAT3 signaling cascade." (PMID 36480232, 2023). "STAT3 is known to play a critical role in the proliferation of gastric cancer cells, which makes it a promising target for the development of antitumor drugs." (PMID 38023173, 2023). "The expression pattern of p-JAK2, which functions upstream of p-STAT3, were lower in the 150μM PA-treated human gastric cancer cell lines (MGC-803, AGS, and SGC-7901) than in the BSA-treated cell lines." (PMID 36672337, 2023). "In conclusion, we identified vortioxetine hydrobromide, a novel dual JAK2/SRC inhibitor, inhibited gastric cancer cell proliferation, through reducing STAT3 dimerization and nuclear translocation in vivo and in vitro." (PMID 37147297, 2023). "In another study, apigetrin caused cell death and decreased cell proliferation in gastric cancer cells by activating ROS generation, the cleavage of PARP, and the STAT3 pathway." (PMID 37509167, 2023). "It has been found that gastric cancer-associated MSCs, by secreting IL-6 and IL-8 cytokines, as well as the JAK2/STAT3 signaling pathway, have caused the polarization of macrophages towards M2 macrophages, which promotes tumor growth." (PMID 38022534, 2023). "In this scenario, the role of the signal transducer and activator of transcription 3 (STAT3) pathway is poorly understood in gastric cancer." (PMID 36979673, 2023). "Our studies have further demonstrated that TNF+ Tregs promote the stemness of gastric cancer cells through the IL13/STAT3 pathway." (PMID 37534250, 2023). "Previous studies have revealed the antitumor mechanism of KAI that inhibits gastric cancer cell proliferation through the interleukin-6/STAT3 pathway." (PMID 36093402, 2022). "This study demonstrated that JAK2/STAT3 signaling pathway regulated various cytokines and growth factors that play an important role in gastric cancer cell growth." (PMID 35207737, 2022). "IL-6/Stat3 signaling pathway promotes the proliferation, invasion and lymphangiogenesis of gastric cancer cells by stimulating JAK-STAT3-VEGF-C signaling pathway." (PMID 36454780, 2022). "Our results indicated that the JAK/STAT3 signaling pathway was involved in the EMT induction process of gastric cancer." (PMID 35517411, 2022). "STAT3 is reported to aggravate progress of gastric cancer via promotion of mesothelial–mesenchymal transition." (PMID 35322746, 2022). "Our findings are consistent with what has previously been reported: that TQ suppressed STAT3 phosphorylation at Tyr705 due to the inhibition of JAK2 activity in gastric cancer." (PMID 35337104, 2022). "The study indicates that inhibition of CAMKK2 has an anti-oncogenic effect in gastric cells regulating phosphorylation of STAT3 through PTK2/c-JUN in gastric cancer." (PMID 35646067, 2022). "IL-6/STAT3 signaling shows significant enhancement in tumor tissue in human gastric cancer datasets." (PMID 35757757, 2022). "Collectively, our study deciphered the molecular mechanisms that p-STAT3 / miR-193a-3p / LAMC1 axis was an essential signaling pathway of gastric cancer peritoneal metastasis." (PMID 35541892, 2022). "STAT3 and p-STAT3 are significantly increased in gastric cancer tissues, which affect the prognosis of patients by regulating the transcriptional activity of downstream factors EZH2." (PMID 36225196, 2022). "In this study, evodiamine prevented the phosphorylation of STAT3 and downregulated the c-Myc expression in gastric cancer cells." (PMID 36135210, 2022). "It was found that propofol increased the levels of ROS and free iron in gastric cancer cells, which led to ferroptosis, and overexpression of STAT3 inhibited propofol-induced ferroptosis." (PMID 36038533, 2022). "PTK2 is also reported to activate STAT3 and is overexpressed in multiple cancers such as gastric cancer." (PMID 35646067, 2022).